PIN1 (peptidylprolyl cis/trans isomerase, NIMA-interacting 1)
Diseases named in the same sentence as PIN1 in open-access papers (continued):
Sharing a sentence is not in itself a finding about the gene and the disease.
cancer (continued). "ATRA/ATO therapy cooperatively ablates Pin1, which can block many cancer-driving pathways and, finally, inhibit the growth of cancer cells." (PMID 35712521, 2022). "In particular, the role of Pin1 in neurodegenerative diseases and cancer has been extensively studied." (PMID 36111342, 2022). "All in all, it is safe to say that Pin1 plays a prominent role in the formation and progress of cancer, and there have been some positive signs showing that Pin1 is a feasible target for drug therapy, as long as the drug is selective enough for Pin1." (PMID 36111342, 2022). "Our understanding of Pin1 in cancer also led to the development of cancer therapeutic drugs targeting Pin1, with some currently in clinical trial phases." (PMID 36111342, 2022). "Prolyl isomerase Pin1, which is highly expressed in both cancer cells and CAFs17, facilitates multiple cancer-driving pathways by regulating the conformational transformation of phosphorylated Serine/Threonine-Proline motif." (PMID 35879297, 2022). "In particular, Professor Kun Ping Lu found that over-activation of Pin1 in cancer interferes with the balance of oncogenes and tumor suppressors, thereby promoting the development of cancer and cancer stem cells." (PMID 36393861, 2022). "Research into PI3K, HSF1, and Pin1 have also suggested that the inverse relationship between AD and cancer stems from a dysregulation in both diseases, but in opposite directions." (PMID 36554301, 2022). "It is thus understandable that, over the years, researchers have attempted to target Pin1 as a treatment for cancer." (PMID 36111342, 2022). "As a critical modifier of multiple cancer-related pathways, Pin1 has been revealed to activate more than 55 proteins, including β-catenin, NF-κB, and AKT." (PMID 35879297, 2022). "Perhaps the most prominent role of Pin1 is in cancer, whereby Pin1 plays a role in many cancer pathways, which resulted in Pin1 being a drug candidate for cancer therapy." (PMID 36111342, 2022). "PIN1 has been recently proposed as a novel and key regulator at the crossroad between cancer and AD." (PMID 35741059, 2022). "Pin1, a cis/trans isomerase of peptidyl-prolyl peptide bonds, plays a crucial role in the pathogenesis of many human cancers." (PMID 35433695, 2022). "Elevated Pin1 expression promotes cancer progression by disrupting the balance between oncogenes and tumor suppressors." (PMID 35461311, 2022). "PIN1 is involved in the development of various cancers and has thus attracted attention as a possible target for cancer therapy, with several PIN1 inhibitors described and tested in preclinical studies." (PMID 36214609, 2022). "In human cancers, Pin1-mediated prolyl cis/trans isomerization induces a conformational change in its substrates and regulates the stability of its target proteins, which are involved in tumorigenesis." (PMID 35433695, 2022). "Recent literature showed that overexpressed Pin1 displays both in cancer cells and CAFs and aggravates PDAC17." (PMID 35879297, 2022). "The current study sets out to discuss the critical role of Pin1 in cancer, and summarizes the recent findings, which show that Pin1 plays multiple roles in tumorigenesis." (PMID 33807199, 2021). "Pin1 upregulates ΔNp63 expression, which enhances cancer cells proliferation by blocking inhibition of E3 ligase WWP1-mediated ubiquitination and degradation." (PMID 33807199, 2021). "Pin1 was known to enhance the proliferation and suppresses the senescence by stabilizing Emi1 in cancer cells." (PMID 33807199, 2021). "PLK1 phosphorylates Pin1 at the Ser65 residue in the PPIase domain and prevents Pin1 ubiquitination, which increases its protein stability in human cancer cells." (PMID 33807199, 2021).
cancer (continued). "Pin1 regulates the self-renewal of Cancer Stem Cells (CSCs) by maintenance the stability of Nanog, octamer-binding protein 4 (OCT4), and MYC." (PMID 34805153, 2021). "While its implication in proliferating cells, and, in particular, in the field of cancer, has been widely characterized, less is known about Pin1 biological functions in terminally differentiated and post-mitotic neurons." (PMID 33083964, 2021). "In multiple cancer types, many studies have shown that the expression levels of PIN1 and levels of Akt phosphorylation are strongly correlated." (PMID 34285767, 2021). "A growing amount of evidence has shown that Pin1 is highly expressed in most cancers and is correlated with poor prognosis in human cancers." (PMID 33807199, 2021). "As an unfavorable function, in contrast, Pin1 overexpression is observed in most cancers and its levels correlate with the aggressiveness of a malignancy and a poor prognosis." (PMID 34067858, 2021). "Cancer cells harboring Pin1 overexpression have phenotypic centrosome amplification, leading to genome instability and higher heterogeneity." (PMID 33807199, 2021). "Growing evidence has shown that Pin1 promotes the p53M-induced gain of new functions (GOFs), leading to aggressive cancers." (PMID 33807199, 2021). "Emerging evidence has demonstrated that Pin1-mediated prolyl isomerization plays pivotal roles under both physiological and pathological conditions, including in human cancers." (PMID 34805153, 2021). "Intriguingly, Pin1 almost acts as the center to regulate the multiple cancer-driving processes in Pro-directed phosphorylation dependent pathways." (PMID 33807199, 2021). "Pin1 overexpression is a pathological feature in numerous cancer tissues and CSCs, and is correlated with poor prognosis in various cancer patients." (PMID 33807199, 2021). "Advancing the pharmacological strategy for Pin1 inhibition, the pre-clinical and clinical studies are also needed to evaluate the safety and efficacy of Pin1 inhibitors for cancer therapy." (PMID 33807199, 2021). "In cancer cells, Pin1 not only represses the DNA damage-induced senescence and apoptosis but also promotes the genome instability such as aneuploidy and centrosome amplification." (PMID 33807199, 2021). "Mounting evidence suggested that Pin1 plays a crucial role in metabolic reprogramming via controlling the function of critical factors involved in aerobic glycolysis in cancer cells." (PMID 33807199, 2021). "It was shown that stimulation of oncogenesis by different oncogenes is connected with prevalent overexpression of Pin1 in the most human cancers." (PMID 34523079, 2021). "Increased observations have indicated that Pin1 plays a critical role in the promotion of invasion and metastasis in many cancers." (PMID 33807199, 2021). "Evidence suggests that Pin1 expression in cancer cells is closely related to the degree of their malignancy, as Pin1 enhances cell proliferation and inhibits apoptosis." (PMID 34535740, 2021). "An increasing body of evidence has indicated that Pin1 acts as a central hub in the promotion of tumorigenesis by augmenting these cancer capacities." (PMID 33807199, 2021). "In cancer cells, high levels of PIN1 amplify the activation of the AKT cascade thus enhancing tumour progression." (PMID 33907248, 2021). "Pin1 inhibition by small molecular compounds suppresses cancer cell proliferation and increases the protein levels of PML and SMRT." (PMID 33807199, 2021). "Pin1 is highly expressed in the bulk of cancers and its inhibition has been found to significantly repress cancer progression." (PMID 33822486, 2021).
cancer (continued). "It was demonstrated that Pin1 inhibits the expression of miR-200b, which can act as a positive feedback loop of Pin1 overexpression in cancer." (PMID 34722255, 2021). "The oncogenic factor PIN1 has been well demonstrated to promote the occurrence and development of various cancers." (PMID 34805153, 2021). "In summary, Pin1 is prevalently upregulated in many human cancers through transcriptional, post-transcriptional, and post-translational regulations." (PMID 33807199, 2021). "Another interesting finding was the reduction of c-Myc expression by EGCG, a transcription factor co-overexpressed with PIN1 in human cancer cells." (PMID 33907248, 2021). "Pin1 is found to regulate IL-22-induced MAP3K8-mediated activation of ERK, JNK and STAT3 for promoting cancer-associated inflammation in the tumor microenvironment." (PMID 33807199, 2021). "In this section, we summarize the regulatory mechanisms of Pin1 that contribute to these cancer capabilities." (PMID 33807199, 2021). "Pin1 is widely overexpressed in human cancers and its reduction significantly represses cancer progression." (PMID 33807199, 2021). "Mounting evidence has revealed that targeting Pin1 is a potential therapeutic approach for various cancers by inhibiting cell proliferation, reducing metastasis, and maintaining genome stability." (PMID 33807199, 2021). "In BC MDA cell lines, PIN1 was found to increase cancer cell metastasis and invasion capabilities by activating the NOTCH pathway." (PMID 32782317, 2020). "When KPT-6566 binds to the catalytic site of Pin1, reactive oxygen species are produced and DNA damage occurs, leading to cell death particularly in Pin1-overexpressing cancer cells." (PMID 33322239, 2020). "In cancer, PIN1’s regulation of MYC has been shown to affect oncogenic transformation, proliferation, redox maintenance, and cell survival." (PMID 32300594, 2020). "PIN1 regulates a large number of these cancer-related targets from extracellular receptors such as NOTCH1 or HER2, to intracellular effector proteins like RAF1 or FAK, and ultimately to transcription factors such as c-MYC, β-catenin, or NF-κB." (PMID 32300594, 2020). "In the following paragraphs we will briefly discuss the evidence linking these gene products to cancer, extending the discussion to PIN1." (PMID 33207722, 2020). "miR-200b-3p, miR-200c-3p, miR-296-5p, miR-874-3p, miR-370, and miR-140-5p, which were always downregulated in cancers, have demonstrated to inhibit PIN1 expression." (PMID 32703934, 2020). "Like cyclin D1, Pin1 has been reported to be overexpressed in various cancers, including breast, colon, liver, and lung cancers." (PMID 31884567, 2020). "In this review, we summarize the findings on the dysregulation, mechanisms, and biological functions of Pin1 in cancer cells, and also discuss the significance and potential applications of Pin1 dysregulation in human cancer." (PMID 32296699, 2020). "Researches have revealed that miR-200b-3p, miR-200c-3p, miR-296-5p, miR-874-3p, miR-370, and miR-140-5p target PIN1 in other cancers." (PMID 32703934, 2020). "Mounting works have demonstrated the invasion- and metastasis-promoting function of Pin1 in human cancer." (PMID 32296699, 2020). "Pin1 promotes tumourigenesis by disrupting the balance between oncogenes and tumour suppressors, and activates many cancer-driving pathways." (PMID 32010480, 2020). "Many therapeutic studies for treating cancers have developed Pin1 inhibitors based on the fact that Pin1 is a generally recognized tumor-promoting factor." (PMID 31884567, 2020). "As a regulator of phosphor-proteins with the Ser/Thr-Pro motif, Pin1 regulates multiple cancer-driving pathways in CCCs." (PMID 32010480, 2020).
cancer (continued). "PIN1 is overexpressed in cancer tissues and CSCs, and correlated with poor clinical outcome in various cancer patients." (PMID 32258027, 2020). "These works commonly report that Pin1 is an excellent target for the diagnosis and therapy of diverse cancers." (PMID 32296699, 2020). "By contrast, depletion of Pin1 in cancer cells leads to elevated Fbw7 expression, which subsequently reduces Mcl-1 abundance, sensitizing cancer cells to taxol treatment." (PMID 32296699, 2020). "Pin1 regulates many biological processes and is also involved in the development of human diseases, like cancer and neurological diseases." (PMID 32266261, 2020). "By contrast, inhibition of Pin1, through RNAi or small molecular inhibitors, significantly reduces the cancer-induced angiogenesis, further supporting the crucial role of Pin1 in angiogenesis." (PMID 32296699, 2020). "Although the tremendous anti-cancer efficacy of the juglone through the Pin1 inhibition is well-known, its potent cytotoxic activity suppresses its selectivity." (PMID 33680036, 2020). "Over-expression of Pin1 can promote tumorigenesis as shown in cancers of the prostate, lung, breast, and so on." (PMID 32117730, 2020). "The prolyl isomerase Pin1 is overexpressed in many cancers and contributes significantly to tumour initiation and progression." (PMID 32010480, 2020). "Pin1 acts as a regulator that promotes cancer progression,and a comprehensive understanding of how Pin1 drives tumourigenesis is essential for cancer prevention, therapeutic,development and the rational selection of combination therapies." (PMID 32010480, 2020). "The post-translational modifications of PIN1, containing oxidation, sumoylation, phosphorylation, and ubiquitination, control the PPIase activity and stability of PIN1, and contribute to the high expression and/or activation of Pin1 in cancer development." (PMID 32258027, 2020). "Pin1 has been demonstrated to be elevated in multiple types of cancer, playing a role in stimulating several cancer-driving processes." (PMID 32630675, 2020). "For instance, selective Pin1 inhibitors can inhibit the phosphorylation of Pin1, thereby inhibit the downstream signal pathways and disrupt the proliferation of cancer cells." (PMID 33519482, 2020). "Recently, two Pin1 inhibitors have been shown to directly bind to the catalytic domain, increase Pin1 degradation, and inhibit Pin1-mediated cell growth in cancer cells." (PMID 32195254, 2020). "Emerging evidence demonstrates that Pin1 promotes cancer by acting as an activator of numerous oncogenes and growth enhancers or as an inactivator of numerous tumor suppressors and growth inhibitors to affect cancer hallmarks." (PMID 32296699, 2020). "A high level of Pin1 overexpression/overactivation closely correlates to poor clinical prognosis of diverse cancers." (PMID 32296699, 2020). "Since deregulation of Pin1 expression and activity has critical effects on the development of cancer and AD, and Pin1 has a specified substrate binding and active site, targeting of Pin1 has been an attractive druggable target." (PMID 32195254, 2020). "PIN1 is highly expressed in human cancers and promotes cancer as well as cancer stem cells by breaking the balance of oncogenes and tumor suppressors." (PMID 32258027, 2020). "In cancer cells, this mitochondrial activity is reduced by Pin1 that catalyzes ATR from cis-isomer to trans-isomer at the phosphorylated Ser428-Pro motif." (PMID 32296699, 2020). "In cancer, Pin1 expression and activity are aberrantly elevated in many malignancies, which are regulated in genetic, transcriptional, post-transcriptional, and PTMs levels." (PMID 32195254, 2020). "In the same work, it has been found that siRNA knockdown of CSNK2β potently inhibited the oncogene Pin1 that supports the notion that CSNK2β is vital for cancer pathogenesis." (PMID 33013272, 2020).
cancer (continued). "Pin1 is initially identified as a regulator of mitosis and gives rise to sustaining proliferative signaling in multiple cancers." (PMID 32296699, 2020). "In this review, we focus on the molecular mechanisms of Pin1 regulation by PTMs and the major impact of Pin1 PTMs on the progression of cancer and AD." (PMID 32195254, 2020). "Pin1 inhibit proapoptotic signals and activate antiapoptotic signals which consequently regulates the cell death resistance in cancer cells." (PMID 32258027, 2020). "More studies are needed to clarify the molecular mechanisms by which Pin1 has opposite effects on the development of cancer." (PMID 32195254, 2020). "We observed that IL‐18 silencing dramatically counteracted the enhanced cell proliferation caused by elevated Pin1 expression and found IL‐18 siRNA completely counteracted the cancer‐promoting effect of Pin1." (PMID 32347623, 2020). "The altered structure and function of these phosphorylated proteins regulated by PIN1 are closely related to cancer development." (PMID 32258027, 2020). "Several studies have demonstrated that inhibition of Pin1 effectively suppresses the growth of various cancer cells, and is considered as a promising target for cancer treatment." (PMID 31884567, 2020). "In this review, we summarize the function of PIN1 in regulating cancer development and small-molecule compounds that exhibit anticancer activities by targeting PIN1." (PMID 32258027, 2020). "Varied transcriptional, translational, and post-translational factors contribute to Pin1 dysregulation in cancer cells." (PMID 32296699, 2020). "This review focuses on the molecular mechanisms of Pin1 regulation by PTMs and discusses the major impact of Pin1 deregulation on the progression of cancer and AD." (PMID 32195254, 2020). "More than ten Pin1 inhibitors have been developed that demonstrate anticancer activity, including sensitizing various cancer cells to chemotherapy." (PMID 33322239, 2020). "Peptidyl-prolyl cis-trans isomerase NIMA-interacting 1 (Pin1) controls the functional switch of phosphoproteins and plays an oncogenic role in human cancer, but the discovery of effective Pin1 inhibitors remains challenging." (PMID 33024085, 2020). "By replacing the phosphate group of D-PEPTIDE with cell-permeable moiety, BJP-06-005-3 also has a better performance in bioavailability and cellular Pin1 selectivity, showing an attractive potential in cancer treatment." (PMID 33024085, 2020). "The majority of cancers present PIN1 overexpression and its down-regulation impairs disease progression, evidence for an oncogenic activity on cancer-driving pathways." (PMID 33207722, 2020). "The KPT-6566 inhibition of Pin1 blocked multiple cancer-driving pathways simultaneously and enhanced the lethal effects of DDP on CCCs in vitro and in vivo." (PMID 32010480, 2020). "Several studies have shown that Pin1 can activate multiple cancer-promoting pathways in human cancers." (PMID 32010480, 2020). "We showed that KPT-6566-mediated inhibition of Pin1 blocked multiple cancer-driving pathways simultaneously in CCCs." (PMID 32010480, 2020). "According to the current literature, Pin1 regulates multiple cancer pathways activating more than 40 oncogenes and inhibiting more than 20 tumour suppressors." (PMID 32010480, 2020). "Pin1 regulates the activities of a spectrum of transcription factors, many of which are involved in cancer cell proliferation and inflammatory response." (PMID 32266261, 2020). "IHC staining indicated that Pin1 expression was positively correlated with IL‐18 expression in PDAC tissues in 39 patients diagnosed with PDAC in our cancer centre." (PMID 32347623, 2020).